IL6 (interleukin 6)
Diseases named in the same sentence as IL6 in open-access papers (continued):
Sharing a sentence is not in itself a finding about the gene and the disease.
bacterial infection (continued). "As one of the cellular inflammatory markers, the level of IL‐6 is low in healthy people and increases with the occurrence of bacterial infections." (PMID 39692539, 2024). "Following stimulation with bacterial lipopolysaccharide, decreased release of IL-8 and IL-6 has been observed, suggesting a limited capacity for an effective response to bacterial infection." (PMID 38915777, 2024). "Various inflammatory markers, including procalcitonin (PCT), C-reactive protein (CRP), erythrocyte sedimentation rate (ESR), and interleukin-6 (IL-6), have been investigated for diagnosing bacterial infections." (PMID 38297213, 2024). "Bacterial infection of the body induces the production of a variety of cytokines, chemokines, and acute chronotropic response proteins, such as IL‐6, IL‐10, C‐reactive protein (CRP), and procalcitonin (PCT), by the body's immune cells." (PMID 39692539, 2024). "Taken together, these data demonstrate that DDX5 blocks IL-6 or TNF-α synthesis during bacterial infection in vitro and in vivo." (PMID 38182816, 2024). "During bacterial infections, IL-6 is vital for activating the STAT signaling pathway, enhancing neutrophil recruitment, and reducing the bacterial load, thereby playing a central role in the host’s defense against P. multocida." (PMID 39770820, 2024). "Human gingival fibroblasts respond to bacterial infection by producing a variety of chemokines and cytokines, including IL-1, IL-6, and MCP-1." (PMID 36793034, 2023). "Circulating CRP and IL-6 are established biomarkers for bacterial infections but have limited value for characterizing disease severity or for making specific prognoses for individual cases." (PMID 36980300, 2023). "Particularly, IL-6 is considered as an important marker for diagnosis of clinical bacterial infections." (PMID 36696504, 2023). "In the early stages of bacterial infection, Mφ are classically polarized to the M1 phenotype, which upregulates the expression of classic inflammatory phase markers, namely iNOS, IL-6, and TNF-α." (PMID 37887741, 2023). "The levels of interleukin (IL)-1β, IL-6 and IL-8 were quantified through a molecular assay, indicating that the peptide was able also to regulate the inflammatory response following bacterial infection." (PMID 37111266, 2023). "Hepcidin, which is an acute-phase reactant, was proven to be upregulated via IL-6 during bacterial infection or inflammation." (PMID 37760781, 2023). "The serum factors IL6, IL8, and IL17 mediate neutrophil recruitment, a hallmark of disseminated bacterial infections." (PMID 38054000, 2023). "A previous study has highlighted the potential of IL-6 and IL-10 as markers to differentiate between G- and G + bacterial infections in children with hematological disorders who have BSI." (PMID 37986183, 2023). "Macrophages play a critical role in fighting bacterial infections by phagocytosis, and possess a specific role in immune regulation by secreting pro-inflammatory cytokines, such as IL-6 and TNF-α." (PMID 36846783, 2023). "In fish, IL-6 is essential for pro-inflammatory immune responses against bacterial infections, enhancing antibody production and activating macrophages (Wang JX." (PMID 37808912, 2023). "The acute phase reactant C-reactive protein (CRP), secreted by the liver in response to cytokines such as interleukin 6 (IL-6), rises within 6–8 h after the onset of acute viral or bacterial infections, aiding in innate immune responses." (PMID 38003780, 2023). "The cytokines TNF-α, IL-6, IL-12/IL-23 p40, and IL-1β were measured in this experimental set-up as they are highly important for the defense against a bacterial infection: the release of TNF-α increases phagocytic capacities of macrophages." (PMID 37654489, 2023). "The levels of cytokines, especially IL-6 and IL-10, usually increase during bacterial infection and are considered to represent early biomarkers to assist in the diagnosis of bacterial infections." (PMID 37953798, 2023).
bacterial infection (continued). "The presence of GIV in murine macrophages was reported to inhibit the expression of proinflammatory cytokines IL-6 and IL-1β during bacterial infection." (PMID 38005948, 2023). "The immune system is strongly influenced by leptin’s strong pro-inflammatory effects, and leptin can be secreted by immune stimuli, such as interleukin (IL)-1, IL-6, lipopolysaccharide (LPS), or bacterial infection." (PMID 37691744, 2023). "IL-6 is a key pro-inflammatory cytokine produced by macrophages upon bacterial infection and is involved in bacterial elimination and tissue repair." (PMID 36834667, 2023). "Despite the overlap of viral and bacterial symptoms, some typical biomarkers that indicate bacterial infection can still be found, including decreased lymphocyte count, elevated white blood cell count, neutrophil count, IL-6, PCT, and hyper C-reactive protein." (PMID 37901822, 2023). "Bacterial infection significantly upregulated mRNA expression levels of Isg15, Mx1, Mx2, Irf-3, Irf-7, Tlr-2, Tnf-α, Cxcl-1, and Il-6 genes." (PMID 37929187, 2023). "The inflammatory factors associated with bacterial infection of IFN-γ, TNF-α, IL-1α, and IL-6 were measured by ELISA analysis." (PMID 36937280, 2023). "This suggests that serum levels of IL-6 and IL-10 can rapidly discern between G + and G- bacterial infections, thereby offering valuable guidance to clinicians for prompt and suitable administration of antibiotic therapy." (PMID 37986183, 2023). "PCT is a diagnostic marker of bacterial infection, which is produced by LPS, TNF-α and IL-6 acting on neuroendocrine cells or special cells in the liver and spleen." (PMID 35436978, 2022). "The bacterial infection accounted for 35.0% (27/77) of patients with low IL-6 and 77.3% (34/44) of patients with high IL-6 (p < 0.001)." (PMID 35391735, 2022). "As previously reported, levels of IL‐6 peak within hours after bacterial infection, especially in severe cases." (PMID 35665444, 2022). "IL-6 gene expression is readily upregulated in cells in response to a wide variety of stimuli (viral and bacterial infections, inflammation and tissue injury, and other cytokines and growth factors)." (PMID 35406728, 2022). "NF-kB is activated in response to viral and bacterial infection stimuli, increased IL-6, IL-8, TNF-α and oxidative stress." (PMID 36560801, 2022). "The specificity and sensitivity of using IL-6 combined with the IL-10 cytokine to identify G- and G+ bacterial infections were both greater than 80%." (PMID 35432366, 2022). "Impaired IL-17 production, possibly due to impaired STAT3-dependent cellular responses to IL-6, IL-21, and/or IL-23, has been proposed as an explanation for the recurrent bacterial infections and CMC seen in these patients." (PMID 35319722, 2022). "Collectively, inborn errors of the IL-6 pathway and their autoimmune phenocopies suggest that IL-6 is crucial for immunity to bacterial diseases, including staphylococcal skin diseases in particular, and for acute-phase inflammatory responses." (PMID 35319722, 2022). "Procalcitonin production occurs in response to lipopolysaccharide, bacterial infection, and cytokines including interleukin 6 (IL-6) and tumor necrosis factor alpha (TNF-α)." (PMID 35531376, 2022). "IL-6 has been most extensively studied within neonatal populations and is generally regarded as a sensitive marker of acute bacterial infection." (PMID 35582414, 2022). "It has been revealed that IL-6 also played a significant role in differentiating various degrees of bacterial infection in NHL patients." (PMID 35463642, 2022). "NFκB mediates responses to viral and bacterial infections by releasing cytokines, including IL-1β, IL-6, and TNF-α." (PMID 36362264, 2022). "IL-6 is one of the newly discovered early markers to assist in the diagnosis of bacterial infections." (PMID 35432366, 2022).
bacterial infection (continued). "During inflammatory condition, such as viral or bacterial infection, there comes to a rapid increase of pro-inflammatory markers such as interleukin 4 (il-4), interleukin 6 (il-6), tumor necrosis factor (TNF) and C reactive protein (CRP)." (PMID 35431842, 2022). "In the present study, the IL-6 level was much higher in patients confirmed as bacterial infection compared with those with non-bacterial infection." (PMID 35391735, 2022). "Hepatic synthesis of the acute phase protein CRP as a response to bacterial infection takes place after stimulation by IL-6 and other proinflammatory cytokines." (PMID 35345614, 2022). "Several recent studies have demonstrated the efficacy of LFA-based systems in quantifying IL-6 in human serum during bacterial infections." (PMID 35149284, 2022). "Of 25 patients that presented both bacterium and other pathogen in the mNGS results, 10 out of 12 (83.3%) patients with high IL-6 were finally confirmed as bacterial infection." (PMID 35391735, 2022). "IL-6 is produced by monocytes and macrophages that are activated during bacterial infection and is the major stimulator of most acute-phase protein production." (PMID 35388320, 2022). "Both IL‐6 and IL‐12 are produced by dendritic cells and macrophages in response to bacterial infections or stress conditions such as tissue injury." (PMID 36176609, 2022). "The concentrations of interleukin 6 (IL-6, sensitive factors for diagnosing bacterial infections), granulocyte (Gran) and white blood cells (WBC) counts were tested to evaluate the inflammatory response." (PMID 35513402, 2022). "While we observed no direct correlation between sIC reactivity and either PCT (indicative of bacterial infection) or IL-6 levels sIC levels were directly associated with CRP and LDH, both undisputed correlates of severe COVID-1911." (PMID 36163132, 2022). "As well-known inflammatory cytokines or chemokines, TNF-α, IL-1β, IL-6, and IL-8 are involved in various types of inflammatory responses and are crucial in inflammatory processes during bacterial infection in bovine mammary glands." (PMID 35681915, 2022). "In this study, a significant increase in IL-6 levels was found in the presence of G+ and G- bacterial infections." (PMID 35432366, 2022). "PCT is synthesized in response to endotoxins or mediators, interleukin (IL)-1β, tumor necrosis factor (TNF)-α, and IL-6, during bacterial infections and has a strong correlation with the severity and extent of bacterial infections." (PMID 35547462, 2022). "CRP, a liver-derived acute-phase protein produced by hepatocytes mainly in response to the inflammatory cytokine interleukin 6 (IL-6), is considered a sensitive biomarker of bacterial infections, cardiovascular events, and inflammatory conditions." (PMID 35407457, 2022). "First of all, in the intestinal tissue was evaluated the amount of IL-6; this cytokine, together with IL-1 and tumour necrosis factor-α, represents an indicator of macrophage activity as a consequence of viral and bacterial infections." (PMID 35507858, 2022). "This determination of IL-6 is helpful for the early evaluation and diagnosis of bacterial infection, and its sensitivity and specificity are higher than those of CRP in current clinical use." (PMID 35432366, 2022). "Although mNGS reported mixed pathogens, 84.6% (33/39) and 83.3% (10/12) of patients presenting high IL-6 were confirmed as bacterial infection in the training and validation cohort, respectively." (PMID 35391735, 2022). "We divided the patients into low (< 390 pg/ml) and high (≥ 390 pg/ml) IL-6 groups, which indicated unlikely and likely bacterial infection." (PMID 35391735, 2022). "In the training cohort, the AUC of IL-6 to predict bacterial infection was 0.741 (95% CI, 0.638–0.844), with a specificity of 85% and sensitivity of 61% at the cut-off value of 390 pg/ml." (PMID 35391735, 2022).
bacterial infection (continued). "Simultaneously, we suggest that patients’ cytokine levels, notably IL-6, be assessed at the time of diagnosis to help detect bacterial infection in NHL patients." (PMID 35463642, 2022). "NGAL acts as mediator of the innate immune response to bacterial infections, and its expression is induced by TNFα and IL-6." (PMID 34944574, 2021). "First, neither the VAT nor the SAT area correlated with systemic inflammation indicated by the C-reactive protein (CRP), interleukin 6 (IL-6) or bacterial infections indicated by procalcitonin (PCT)." (PMID 33861804, 2021). "As expected, bacterial infection induced a systemic inflammatory response characterized by increased plasmatic levels of TNFα, IL-6, IL-12, IFNγ and KC/GRO (CXCL-1) compared to PBS-treated mice." (PMID 34437647, 2021). "IL-6, an immunomodulator mainly produced by T cells, macrophages, or endothelial cells, is found with involvement of autoimmune disorder, bacterial infection and metabolic side action." (PMID 34334083, 2021). "Zarkesh et al11 considered that IL‐6, CRP, WBC, and absolute neutrophil counts have diagnostic value to predict serious bacterial infection." (PMID 34725873, 2021). "Upon infection, in particular bacterial infection, pro-inflammatory cytokines such as IL-1 and IL-6 are released into the circulation in response to pathogen-associated molecular patterns (PAMPs)." (PMID 34079538, 2021). "IL-1 and IL-6 have been studied as biomarkers for bacterial infection but fail to show sufficient specificity and sensitivity in both children and adults, most likely because of the extremely short half-life of both cytokines." (PMID 34079538, 2021). "Odontogenic MSCs are vulnerable to LPS-triggered bacterial infections, and they respond by secreting inflammatory mediators, such as IL-6, and with mineralization." (PMID 35052527, 2021). "Upon sensing bacterial infection, they release cytotoxic molecules and cytokines, such as nitric oxide (NO) and interleukin 6 (IL6)." (PMID 33670458, 2021). "Production is, however, activated in all parenchymal organs in response to bacterial infection, mediated by cytokines: interleukin-6 (IL-6), tumor necrosis factor-α (TNF-α) and interleukin-1β (IL-β)." (PMID 34577795, 2021). "Further, treatment by øKp_Pokalde_002 significantly reduced the inflammations caused by bacterial infection and downregulated the levels of the pro-inflammatory cytokine (TNF-α and IL-6) expression." (PMID 34485172, 2021). "IL-6 is an important inflammatory factor whose levels sharply increase in the process of bacterial infection and seriously affect the lung microenvironment." (PMID 34544355, 2021). "The balance of anti-inflammatory (IL-10) and proinflammatory (IL-12, IF-g, and IL-6) cytokines modulates the composition and the maturation of the phagosome (phagosome conversion) in its fusion with the lysosome during the bacterial infection process." (PMID 34356768, 2021). "Bacterial infection, Child–Pugh C classification, serum C-reactive protein, IL-6, percentages of cMo, iMo, and TiMas within the monocyte compartment, percentage of CD62L+ monocytes, and pDC/cDC ratio were associated with 90-day mortality." (PMID 33723292, 2021). "This modulation of immunity is also supported by decreased levels of cytokines responsible for controlling bacterial infections, such as IL-1β, IL-6, IL-9, IL-12, TNF-α, IL-17, and IFN-γ, observed in the serum of the WT mice." (PMID 32139610, 2020). "In various bacterial infection models, IL-6 was reported to induce DLL-1 expression in monocytes through the activation of STAT3." (PMID 32635645, 2020). "We showed that pro-inflammatory cytokine (IL-6 and IL-8) expression was induced by LPS or bacterial infection but decreased by treatment with O. japonica extract following bacterial infection." (PMID 32244806, 2020). "The body temperature and plasma inflammatory cytokines (TNF-α, IL-6) levels increased after bacterial infection at 24 h in all groups." (PMID 32221396, 2020).
bacterial infection (continued). "M1 polarization occurs via stimulation with several pro-inflammatory signals (e.g., LPS and IFNγ, with ensuing TNFα, and IL-6 production), as are normally elicited early after bacterial infection of the urinary tract." (PMID 32849562, 2020). "The protective role of IL-6 during bacterial infections is regularly mediated through the regulation of other inflammatory cytokines." (PMID 33322581, 2020). "IL-6 has emerged as a key cytokine during bacterial infections, with complex effects on cells of the immune system and context-dependent proinflammatory described properties." (PMID 33322581, 2020). "Th17 cells induced by a Th2 cytokine (IL-6) are recognized as a pivotal player in modulating autoimmune response and combating bacterial infections." (PMID 33015714, 2020). "In several studies IL-6 levels in the serum have been found to correlate with either bacterial infections or disease severity in patients with CAP44–47." (PMID 32770049, 2020). "SOCS family proteins were considered as the important regulators of inflammatory responses (like interferons and cytokines; IL6, TNFα) and being significantly induced by broad range of bacterial infections." (PMID 33585275, 2020). "Specifically, CT and TT genotypes of rs3804099 are linked with resistance to bacterial infection due to higher TNF-a, IL-1B and IL-6 production in peripheral blood monocytes than CC homozygotes." (PMID 33328979, 2020). "The interplay between IL-10, IL-12p40, and IL-6 intense affected the outcomes of macrophage function and bacterial infection." (PMID 32117813, 2020). "IL-6 and IL-17 are secreted by airway cells activated in response to bacterial infection and are present in large concentrations in CF airways." (PMID 32528461, 2020). "Through bacterial infection or stimulation of human primary oral cells with their components, cells secrete various inflammatory mediators, such as IL-6 and IL-8." (PMID 32244806, 2020). "The main cause of AKI is bacterial infection, which worsens circulatory dysfunction through the release of HMGB1 and IL-6." (PMID 33061824, 2020). "Within our data, the most reliable signature for non-bacterial inflammation was high levels of IL-6 with low levels of IL-17, and the most reliable signature for bacterial infection was high levels of IL-6 with high levels of IL-17." (PMID 33409494, 2020). "The concentrations of interleukin-6 (IL-6), sensitive factors for diagnosing bacterial infections, and white blood cells (WBC) counts were tested to evaluate the inflammatory response." (PMID 32895387, 2020). "As an example, Interleukin 6 (IL-6) is routinely used as a biomarker for the acute response of the immune system and serves as an early indicator of bacterial infection." (PMID 33224151, 2020). "Four patients with autoantibodies against IL-6 who developed severe bacterial infections have been published to date." (PMID 32419033, 2020). "Further, patients with autoantibodies against IL-6 and severe bacterial infections have been identified (Doffinger and von Bernuth unpublished data)." (PMID 32419033, 2020). "STAT1 is largely restricted to mediating the effects of IFNs, animals that lack STAT1 are exquisitely sensitive to microbial infections; while STAT3 mediates the effects of IL-6 and other gp130 ligands, and regulates the host response to bacterial infection." (PMID 33361763, 2020). "C-reactive protein (CRP) is an acute phase protein and the production of CRP is stimulated by a proinflammatory cytokine, interleukin 6 (IL-6), involving in the host defense against bacterial infections." (PMID 32398008, 2020). "Our results were also in agreement with the previous reports and revealed slight yet significant increase in IL-6 and IL-8 levels following bacterial infection in all the cells compared to unstimulated controls." (PMID 32218782, 2020).